ATF4 (activating transcription factor 4)
Diseases named in the same sentence as ATF4 in open-access papers (continued):
Sharing a sentence is not in itself a finding about the gene and the disease.
tumor (continued). "In response to hypoxic conditions and other stresses of the tumor microenvironment, ATF4, a master transcriptional effector of the integrated stress response, is a critical mediator of cancer cell survival." (PMID 29416636, 2018). "The protein expression of IFNAR1 was significantly correlated with those of IRF1 and PDL1 in both tissues but with those of ATF4 and eIF2α only in the tumor tissue." (PMID 30305853, 2018). "As one of three arms of the UPR response, the PERK/EIF2α-ATF4 promotes tumorigenesis by activating autophagy and enhancing tumor formation." (PMID 29581853, 2018). "The protein levels of IRF1, eIF2α, and ATF4 were consistently correlated in the tumor tissues but to various extents in the normal ones." (PMID 30305853, 2018). "The meta-analyses results indicate that in a subset of tumour types, high IMPACT expression associates with decreased expression of stress response pathways and the key ISR effector genes ATF4 and DDIT3 (CHOP)." (PMID 30466445, 2018). "The protein levels of ATF4 and eIF2α were significantly correlated in the tumor tissues of all subjects and the subgroups of adenocarcinoma and SCC and in the normal one of SCC." (PMID 30305853, 2018). "The anti-cancer drug ONC201 induces tumor cell death through ATF4-mediated transactivation of the proapoptotic protein TRAIL and its receptor, death receptor 5 (DR5)." (PMID 28860159, 2017). "Western blot analyses and immunohistochemistry of the harvested tumor tissues also revealed that (S)-crizotinib treatment increased the levels of ATF4, CHOP, p-eIF2a indicating activation of the ER stress pathway." (PMID 28882182, 2017). "It has been found that ATF4 mediates ER stress-induced cell death in tumor cells treated with the chemotherapeutic agents." (PMID 28030827, 2017). "To correlate these findings with the GLS knockdown data in our xenograft model SUM-159PT, we analyzed these tumor lysates for both ATF4 levels and phospho-P70 S6K." (PMID 28950000, 2017). "Recently, it has been suggested that ATF4 can act in concert with Nrf2 to induce HMOX1 expression as a protective mechanism preventing apoptosis of tumor cells." (PMID 28129777, 2017). "In brief, we demonstrated that continuous oral feeding with fucoidan significantly reduces tumor volumes and induces ATF4 and CHOP protein expressions in LLC1-bearing mice in vivo." (PMID 28332554, 2017). "Increased ATF4 expression facilitates tumorigenesis by modulating transcription of genes involved in tumor cell proliferation." (PMID 28860159, 2017). "Mechanistically, transcription of many essential genes involved in tumor cell proliferation are regulated by ATF4." (PMID 28881638, 2017). "RT-qPCR assays with RNA samples obtained from skin lesions of L. braziliensis infected patients or skin biopsies from healthy individuals showed that samples from patients display elevated ATF4 expression." (PMID 29213084, 2017). "ATF4 can protect tumor cells against stresses and a range of cancer therapeutic agents via the regulation of cellular adaptation to adverse circumstances." (PMID 29216929, 2017). "It remains that strategies to target ATF4 expression will have to be considered in the complexity of tumor heterogeneity and it is likely that combined or sequential therapies will be necessary." (PMID 28460466, 2017). "It has been demonstrated that the eIF2α-ATF4 pathway is essential for tumor cell survival and proliferation in response to various stress conditions." (PMID 27708226, 2016). "Our findings reveal a key novel function of eIF2α-P in the regulation of the interaction between CML cells and tumor stroma in response to stress and point to ATF4 as a potent therapeutic target." (PMID 27802179, 2016). "Further limitations surround the potential up‐regulation of other glutamine transporters by adaptive mechanisms such as ATF4 transcription; this will need to be monitored for potential compensation mechanisms in tumours." (PMID 25693838, 2015).
tumor (continued). "In previous studies, ATF4 was shown to mediate the VEGF-dependent tumor growth and angiogenesis triggered by osteopontin (OPN)." (PMID 25883982, 2015). "ATF4 is overexpressed in solid tumors and is essential for tumor cell survival in various mouse and human cancers whereas elimination of ATF4 in cancer cells induces apoptosis." (PMID 25692096, 2015). "It has been found that ATF4 expression is increased in response to tumor microenvironment stresses including oxygen deprivation, and it takes part in the adaptation to hypoxia." (PMID 25883982, 2015). "Previous studies have shown that ATF4 expression is frequently induced in primary tumors and tumor cell lines." (PMID 26565589, 2015). "Suppression of ATF4 expression inhibits tumor survival and proliferation in response to both amino acid deprivation and glucose deprivation." (PMID 25941664, 2015). "The results suggest that ATF4 drives basal ULBP1 expression in multiple tumor cell lines, perhaps reflecting constitutive activation of underlying stress pathways." (PMID 26565589, 2015). "Our findings highlight the importance of ATF4 dysfunction in promoting tumor progression and metastasis and implicate it as a potential therapeutic target for ESCC." (PMID 25078779, 2014). "Taken together, these results suggest that MMP-2 and MMP-7 are involved in and essential for ATF4-mediated tumor invasion and metastasis." (PMID 25078779, 2014). "To further investigate the influence of ATF4 silencing on in vivo tumor metastasis, we injected TE-1HM-siATF4 or TE-1HM-SCR cells into nude mice through their tail veins." (PMID 25078779, 2014). "The prognostic value of ATF4 protein expression in patient subgroups that were stratified according to tumor clinical stage was also analyzed." (PMID 25078779, 2014). "ATF4 expression is increased in response to ER stress and a variety of tumor microenvironmental stresses including low glucose, hypoxia, amino acid depletion." (PMID 25393282, 2014). "To determine the role of ATF4 in tumor metastasis, we knocked down ATF4 expression with the indicated lentiviral shRNA." (PMID 25078779, 2014). "When global translation is inhibited by the phosphorylation of eIF2α, the translation of certain mRNAs, such as GCN2, ATF4 and X-linked inhibitor of apoptosis protein (XIAP), is increased and this promotes tumor cell survival and chemoresistance." (PMID 23354132, 2013). "Basal levels of ATF4 have been shown to be increased in some human tumor lines, although the pathway that is responsible for its expression in these lines was not determined." (PMID 23144714, 2012). "Data supports that the CHOP/ATF4 arm of the unfolded protein response (UPR) which is responsible for TRIB3 upregulation during hypoxia protects tumor cells during hypoxia." (PMID 23185332, 2012). "Recently, overexpression of ATF4 was reported to be prominent in a wide variety of tumors and to protect tumor cells against multiple stresses, as well as a range of cancer therapeutic agents." (PMID 22363646, 2012). "Finally, in vitro rescue experiments and in vivo efficacy studies revealed that the ATF4‐PFKFB3 axis is necessary for the HCC tumor growth and metastasis." (PMID 40919132, 2025). "Recent studies suggest that the ATF4-driven activation of lipogenesis is accompanied by a paradoxical suppression of lipid utilization, indicating a metabolic reprogramming strategy that favors biomass accumulation and tumor growth under stress." (PMID 40951358, 2025).
tumor (continued). "Furthermore, in SNU719 xenograft models, ATF4 silencing partially reversed pyrotinib’s therapeutic efficacy, manifesting as attenuated tumor growth suppression (reduced volume and weight) and elevation of Ki-67 proliferation indices." (PMID 40830980, 2025). "Loss of TINCR leads to stress-induced ATF4 activation, immune evasion, and resistance to BRAF/MEK inhibitors in melanoma cells, highlighting its role at the intersection of immune regulation and tumor progression." (PMID 40777108, 2025). "Furthermore, exposure to key metabolic constraints of the tumor microenvironment, such as limited asparagine levels, further upregulates ATF4 expression in T cells, reinforcing its role as a stress sensor in immune adaptation." (PMID 40335738, 2025). "Moreover, heightened ATF4 expression is crucial for tumor cell growth and acts as a defense mechanism against tumor cell death." (PMID 39870616, 2025). "In addition to its role in metabolic adaptation, ATF4 plays a dual role within the tumor microenvironment, influencing both pro- and antitumor immune responses." (PMID 40335738, 2025). "The A113 splice mutation enhances tumorigenesis through multiple mechanisms, including stabilization of the 43S preinitiation complex, upregulation of ATF4, and suppression of EIF2α phosphorylation, collectively leading to increased protein synthesis and tumor growth." (PMID 40363930, 2025). "Moreover, lncRNAs such as LINC00346 and TINCR connect ATF4 signaling to tumor immune evasion, revealing their dual roles in both immune homeostasis and cancer immunology." (PMID 40777108, 2025). "Furthermore, genetic ablation of downstream PERK effectors (CHOP or ATF4) in tumor stroma substantially attenuates MDSC-mediated immunosuppression through downregulation of critical molecular mediators including C/EBPβ, phosphorylated STAT3, and IL-6231." (PMID 41209558, 2025). "ATF4 and c-MYC activation induced by EIF1AX mutations enhance amino acid transporter expression and increase mTOR sensitivity to amino acid availability, promoting tumor growth." (PMID 40363930, 2025). "Overall, our study underscores the significance of METTL1 and its role in the m7G modification of ATF4 as a means of regulating cSCC tumor progression, offering a foundation for the further exploration of innovative therapeutic approaches to clinical cSCC treatment." (PMID 39870616, 2025). "However, the increased expression of ATF-4 supports cell proliferation and can be hijacked by cancerous cells to sustain rapid tumor growth." (PMID 41154628, 2025). "In this study, we propose that ATF4 may promote tumor growth and metastasis by activating the expression of ARL5B, thereby influencing the SKIP/Kinesin-1 pathway." (PMID 41451209, 2025). "The downregulation of ATF4 in RB cells is a key factor in tumor inhibition." (PMID 41451209, 2025). "Finally, we found that NKT inhibited the growth of tumor in GBM orthotopic mice model through activation of ATF4-CHOP-CHAC1 axis." (PMID 39819316, 2025). "Functionally, overexpressing ATF4 reversed the anti-tumor effect of METTL1 knockdown." (PMID 39870616, 2025). "ATF4 overexpression mitigated the impact of METTL1 knockdown on tumor growth and weight." (PMID 39870616, 2025). "We have found that a Keto diet induces ATF4 expression in tumor tissues." (PMID 38838145, 2024). "In contrast, ATF4 knockdown may induce ferroptosis and control tumor parenchyma and blood vessel growth." (PMID 38808552, 2024). "Overexpression of ATF4 has been found to significantly promote tumor cell growth and invasion." (PMID 38601083, 2024). "It activates the intracellular tumor-suppressive stress response via upregulating the critical ER stress marker DNA damage-inducible transcript 3 (DDIT3) through the regulation of activating transcription factor 4 (ATF4)." (PMID 38568424, 2024).
tumor (continued). "LSD1 ablation could inhibit ATF4 activation, resulting in aberrant integrated stress response and sensitizing TICs to stress-induced cell death, ultimately suppressing tumor progression." (PMID 38601083, 2024). "Additionally, ATF4 promotes tumor-mediated neurotoxicity and tumor angiogenesis, which can be alleviated by ferroptosis inducers such as Erastin and RSL3." (PMID 39021564, 2024). "Concurrently, protein expression of the eIF2α-ATF4-CHOP pathway was upregulated in tumor tissues." (PMID 38509524, 2024). "Previous reports also claim that the activation of GCN2 and subsequent nuclear entry of activating transcription factor 4 (ATF4) could play a role in tumor angiogenesis." (PMID 39065567, 2024). "Nrf2 and activating transcription factor 4 (ATF4) control its enhanced levels in tumor cells." (PMID 39125992, 2024). "ATF4 could promote tumor angiogenesis and shape the vascular architecture in a xCT-dependent manner." (PMID 38601083, 2024). "This RGS2/ATF4 axis is a potential target to reduce tumor relapse and resistance of NSCLC patients." (PMID 38601083, 2024). "We investigated the correlation between ATF4 signaling and the immune tumor microenvironment." (PMID 39139391, 2024). "Additionally, our study explored the connection between ATF4 signaling score and tumor immunologic characteristics." (PMID 39139391, 2024). "AsC could upregulate cellular ROS levels, induce ER stress in tumor cells, activate the PERK/eIF2α/ATF4/CHOP signaling pathway, cause tumor ICD and change tumor immunity microenvironment eventually." (PMID 38132921, 2023). "Therefore, the PERK/eIF2α/ATF4 pathway is often considered to play a key role in tumor progression and the development of cancer therapies." (PMID 37790807, 2023). "However, ATF4 showed reversed expression trends with low expression in most tumor tissues compared to normal tissues." (PMID 36627482, 2023). "Similarly, ATF4 is able to mediate the invasion process of tumor cells during ER stress through PERK/eIF2α/ATF4/CHOP axis." (PMID 37462732, 2023). "Moreover, pharmacological inhibition of eIF2α phosphorylation using integrated stress response inhibitor (ISRIB) or depletion of ATF4 partially abolished the tumor-promoting effects of ETHE1 on TNBC metastasis both in vitro and in mice." (PMID 37834012, 2023). "Notably, inhibition of eIF2α phosphorylation through ISRIB or ATF4 knockdown partially abolished the tumor-promoting effect of ETHE1 overexpression." (PMID 37834012, 2023). "In addition, the activation of PERK/eIF2α/ATF4/CHOP axis suppresses tumor progression and triggers cell death." (PMID 37316499, 2023). "Since high tumor ATF4 activity strongly correlates with poor cancer prognosis, this could explain in part why PRRC2A is associated to cancer." (PMID 36869665, 2023). "In the process of ERS‐induced epithelial‐mesenchymal transformation (EMT), GRP78/PERK signaling pathway is activated, which promotes nuclear translocation of ATF4 and increases the transcriptional activity of interleukin‐like met inducers, which accelerates tumor progression." (PMID 36999888, 2023). "Importantly, Pmel+ATF4-KI Teff cells were more effective in killing tumor cells in vitro and controlling tumor growth in vivo." (PMID 37550596, 2023). "It is intriguing that in the tumour growth/resection experiments using the global ATF4 KO mice, we did not observe deficiencies with wound closure following surgical resection." (PMID 35654839, 2022). "Moreover, ATF4 overexpression inhibited tumor proliferation and AR expression both in vitro and in vivo." (PMID 35013318, 2022).
tumor (continued). "This study indicated that POU4F3 may work as a tumor suppressor in LUAD via regulating the PERK/eIF2α/ATF4/CHOP pathway." (PMID 35069902, 2022). "To this end, we assessed the ATF4 expression on nuclear extracts of tumour explants." (PMID 35367410, 2022). "Moreover, we analyzed the proliferative index in tumor sections and found that the expression levels of Ki-67, a marker of proliferation, and AR were much lower in ATF4-overexpressing xenograft mice than in the control xenograft mice." (PMID 35013318, 2022). "In tumor cells, ATF4 demonstrates contrary functions in different conditions." (PMID 35372041, 2022). "However, the combination of GPR78 and RET interferes with the interaction between RET and ATF4, down-regulating ATF4 and inhibiting the anti-tumor effect of BTZ, thus leading to chemotherapy resistance." (PMID 36551309, 2022). "Therefore, tumor progression needs proteostasis adjustment by the upregulation of ATF4 and the modulation of cellular stress responses." (PMID 36497032, 2022). "Moreover, ASS1 overexpression effectively improves the anti-tumor effect of chemotherapy by activating the PERK/eIF2α/ATF4/CHOP axis." (PMID 35910381, 2022). "However, under our experimental conditions, whereas loss of GCN2 led to a sharp reduction in tumor growth in the 22Rv1 xenograft model, deletion of ATF4 only delayed tumor growth." (PMID 36107759, 2022). "ATF4 or GCN2 expression abrogation significantly inhibited tumor growth in MEFs." (PMID 36497032, 2022). "To delineate the role of host ATF4 in the sequence of events leading to tumour growth, we performed transcriptional profiling at the single-cell level (single cell RNA sequencing (scRNA-seq)) in small (150 mm3) and large (300 mm3) B16F10 tumours grown in Atf4WT/WT and Atf4Δ/Δ mice." (PMID 35654839, 2022). "The same study showed that the ATF4 factor is responsible for the regulation of glutamate antiporter xCT (SLC7a11) expression, which is a critical tumor-induced intoxication of the brain’s microenvironment, and glutamate secretion in human malignant glioma specimens." (PMID 35409080, 2022). "However, ASS1 in T cells is still poorly expressed because of the tight chromosome that cannot bind to ATF4 and CEBPβ, resulting in impaired T-cell anti-tumor immunity." (PMID 36231064, 2022). "Therefore, we knocked down ATF4 (siATF4) in renal CAKI1 tumor cells and compared the expression of SLC7A11, GCLM, and GLS after 1 and 24 h of hLcn-2 stimulation to scRNA-treated cells." (PMID 34069743, 2021). "However, PERK-eIF2α-ATF4 pathway has been shown to take part in a diametrically opposed function as a tumor suppressor." (PMID 33599798, 2021). "The time-course evaluation showed that PT administration immediately induced ATF4 upregulation in the tumor tissues within several hours, suggesting that PT had been successfully delivered to the tumor tissue and induced amino acid depletion or inhibited glycosylation in vivo." (PMID 34623325, 2021). "New drug combinations targeting mTORC1, ATF4 or the adaptation state more broadly, could forestall drug resistance and tumour relapse." (PMID 33741929, 2021). "ATF4 increases tumor angiogenesis and vascular structure shaping in an xCT activity-dependent manner, and downregulating ATF4 expression can enhance the sensitivity of nerve tumor cells, which control the proliferation and vasculature of tumors, to ferroptosis." (PMID 34869322, 2021). "Importantly, we found that rapamycin treatment strongly decreased ATF4 protein levels in these tumors with a concomitant decrease in glutathione levels, measured by LC-MS in tumor metabolite extracts." (PMID 33646118, 2021). "The eIF2α- ATF-4 pathway is more prominent in the tumor cells." (PMID 34717757, 2021).